TLR4 (toll like receptor 4)
Diseases named in the same sentence as TLR4 in open-access papers (continued):
Sharing a sentence is not in itself a finding about the gene and the disease.
tumor (continued). "Using transcriptomics and integrative biology, we have also identified Tlr4-modulated gene expression pathways that distinguish the tumor promotion stage (Protocol 1) and the progression stage (Protocol 2) of tumorigenesis." (PMID 19925653, 2009). "We previously demonstrated that lung carcinogenesis was enhanced in mice with dysfunctional Tlr4, likely due to greater chronic inflammation during tumor promotion in the Tlr4 mutant mice relative to the Tlr4 wild type strain." (PMID 19925653, 2009). "Work with this model showed that deletion of Tlr4 decreased tumour formation, suggesting that bacteria use the receptor to promote colorectal carcinogenesis." (PMID 19672421, 2009). "We suggest that these pathways and interactions amongst the genes identified during tumor promotion influence the TLR4-mediated response observed during progression of tumorigenesis." (PMID 19925653, 2009). "LY96 encodes MD2, an accessory molecule required for the activation of toll-like receptor-4, which promotes cell survival and induces the secretion of immunosuppressive molecules that promote tumor evasion from immune surveillance." (PMID 18030354, 2007). "Moreover, BGN's activation of innate immune receptors such as TLR2 and TLR4 further underscores its potential as a universal modulator of tumor immunity." (PMID 41328346, 2026). "Histone lactylation, written by p300 at H3K18 and related lysine residues, is context-dependent: physiological pulses during exercise and sleep are adaptive, while chronic accumulation in diabetic microglia drives neuroinflammation via TLR4/NF-κB, and excess in tumor cells enables senescence bypass." (PMID 42318360, 2026). "Interestingly, our study found that BGN secreted by PTC tumor cells drives M2 macrophage polarization through the TLR4 signaling pathway, thereby exerting an anti-inflammatory effect." (PMID 41328346, 2026). "TLR4 has the potential to both inhibit and promote tumor growth." (PMID 41601666, 2026). "Besides, with the addition of recombinant CTSC or tumor debris, TLR4 was colocalized with RAB5 (the indicator of early endosome) in macrophages, consistent with the point that TRIF adaptor was preferentially activated in endosomes." (PMID 41480760, 2026). "From there, polymorphonuclear myeloid-derived suppressor cells (PMN-MDSC) rise via a TLR4-overexpressed pathway (associated with CCA progression and worse disease outcomes) and the CXCL1–CXCR2 axis, promoting chronic inflammation, tumor proliferation and reducing anti-tumor activity." (PMID 40310432, 2025). "TLRs regulate host defense mechanisms, elicit pro-tumorigenic responses, and could be deemed potential biomarkers to monitor tumor progression, specifically TLR4 in tumor survival and chemoresistance, and TLR2 in metastatic progression." (PMID 40809181, 2025). "Consequently, MyD88 activates TLR4 signaling, leading to the expression of anti-apoptotic proteins, and increased pro-tumor inflammation." (PMID 40560045, 2025). "The activation of TLR4 in macrophages can promote the enhancement of macrophage presentation function and the chemotaxis of cytotoxic lymphocytes to exert the function of killing tumor cells." (PMID 40727252, 2025). "Moreover, according to prior reports, F. nucleatum modulates the local immunity of cancers by creating a permissive tumor microenvironment, insensitive to pro inflammatory signals, with low TLR4 signaling and recruitment of type 2 Macrophages64." (PMID 39743544, 2025). "Studies have shown that TLR4 signaling can influence PD-L1 expression and T-cell responses, particularly relevant given recent evidence linking innate immune signaling to tumor immune evasion strategies." (PMID 40703545, 2025). "Sustained activation of TLR4 signaling promotes tumor metastasis through multiple mechanisms." (PMID 41488647, 2025). "Recent studies revealed complex TLR4/MyD88 signaling interactions with tumor progression." (PMID 40703545, 2025).
tumor (continued). "The TLR4/Myd88/NF-κB signalling axis promotes the development of tumours." (PMID 39735680, 2025). "The resulting hybrid nanoparticles (HM-NPs) promoted the DC phagocytosis of tumor antigens via TLR4 signaling, driving DC maturation and establishing durable tumor protection, thereby highlighting the potential of plant-derived nanomaterials in personalized immunotherapy." (PMID 40429976, 2025). "Therefore, a strategy containing chemotherapeutic agent, TLR-4 agonist, and PD-1/PD-L1-targeting peptide would effectively enhance the anti-tumor immunity and inhibit the aggressive growth of OS." (PMID 40264674, 2025). "In the context of tumor immunity, our findings of predominantly low TLR4 expression in advanced stages could be explained by emerging insights into immune checkpoint regulation." (PMID 40703545, 2025). "In conclusion, this study demonstrated an inverse correlation between the expression of PD‐L1 and TLR4 at deep and superficial tumor fronts, suggesting that it may identify distinct immunological groups." (PMID 40762187, 2025). "TLR4 increases inflammatory responses and tumor growth following paclitaxel, suggesting TLR4 may be the underlying cause of chemotherapy resistance." (PMID 40878805, 2025). "Indeed, LPS as ligand for TLR4 activation during tumor progression has been validated in gastric tumors." (PMID 40124677, 2025). "Increased CD14‐labeled monocytes in the spleen of tumor‐bearing mice may activate the therapeutic potential of innate immunity through the TLR4 signaling pathway." (PMID 40289661, 2025). "The BCG cytoplasmic membrane is composed of a plasma membrane surrounded by lipid-attached peptidoglycan (PG) and arabinogalactan (AG), which are agonists of TLR2 and TLR4 and can be used as an adjuvant for tumor vaccines to enhance the maturation and migration of DCs in the tumor microenvironment." (PMID 40284501, 2025). "Previous studies have indicated that high TLR4 expression in tumour cells may alter the tumour microenvironment through various mechanisms." (PMID 40696496, 2025). "P. acnes significantly increases in GC tissues infected with H. pylori, activating the TLR4/PI3K/Akt signaling pathway, inducing polarization of M2-type tumor-associated macrophages (TAMs), and promoting the secretion of immunosuppressive factors IL-10 and CCR-2." (PMID 40529304, 2025). "Based on this evidence, we hypothesized that inhibition of TLR4 in tumor-bearing mice would suppress fusogenicity of M-LECPs, leading to reduction in new vessels and decreased node metastasis." (PMID 40507286, 2025). "In the Lewis lung cancer mouse model, TLR4 also mediated the development of tumor-associated fatigue, a process independent of the activation status of macrophages and microglia." (PMID 40166469, 2025). "However, TLR-4 inhibitors abrogate the immunomodulatory effects of cinnamaldehyde, underscoring the essential role of TLR-4 in stromal immunomodulation within the tumor microenvironment." (PMID 40404908, 2025). "Moreover, in macrophages, BGN promoted proliferation and migration, and induced M2-like polarization by activating the NF-κB signaling pathway through TLR4, suggesting its multifaceted role in modulating the tumor microenvironment." (PMID 41465449, 2025). "Pathway enrichment and tumour microenvironment analyses revealed significant associations between NPF‐related genes and immune cell types, particularly highlighting the link between TLR4 expression and macrophage infiltration." (PMID 40696496, 2025). "A number of studies have reported the role of TLR4 in tumor motility, invasion and metastasis." (PMID 40124677, 2025). "Notably, genetic ablation of either CXCL10 or TLR4 significantly reduces tumor growth and systemic MDSC accumulation, illustrating the mechanistic diversity of CXCL10-mediated immunosuppression." (PMID 41516196, 2025).
tumor (continued). "The transcription factor NF-κB, associated with TLR4 and B1R, showed no significant changes in mRNA expression in endothelial cells exposed to tumor microenvironments, with or without DBK." (PMID 40284027, 2025). "Combining TLR4 agonists and antigens with magnetic nanoparticles mimicking pathogens to enhance their uptake and processing by antigen-presenting cells, activated T cell-mediated anti-tumor immune responses." (PMID 41568029, 2025). "Furthermore, endogenous ligands like Peroxiredoxin-1 can activate TLR4, stimulating tumor angiogenesis and expansion in murine models, solidifying the role of TLR4-mediated inflammation in PCa pathogenesis." (PMID 41162970, 2025). "Furthermore, TLR-4 can affect tumor resistance by modulating key processes within the tumor microenvironment, including epithelial-mesenchymal transition (EMT), stemness maintenance, and stromal immunosuppression." (PMID 40404908, 2025). "Furthermore, TLR4 modulators can be explored to balance the inflammatory response and reduce immunosuppression within the tumor microenvironment." (PMID 40762187, 2025). "Additionally, TLR4 activation leads to the activation of CyclinD1 and stimulates the involvement of cells in the process of tumor formation and progression during the G1/S phase." (PMID 39708583, 2025). "Furthermore, HMGB2 drives the recruitment of tumor-associated macrophages (TAMs), MDSCs, and Tregs, promoting an immunosuppressive TME via RAGE and TLR4 signaling." (PMID 40396172, 2025). "We also analyzed TLR4 expression in the surrounding non-tumor tissue." (PMID 40647480, 2025). "Similarly, in non-small cell lung cancer, downregulation of HMGB1 sensitizes tumor cells to radiation by inhibiting the TLR4/NF-κB signaling axis." (PMID 40969278, 2025). "Research by Jie Xu and colleagues showed that SeNPs significantly activated the Tlr4/Myd88/NF-κB signaling pathway, leading to the conversion of M2 macrophages into M1 macrophages and effectively stimulating an anti-tumor immune response in mice with the H22 tumor model." (PMID 40182029, 2025). "We also found that HMGB1, a TLR4 agonist that can induce IL-24, is highly upregulated in calcipotriol-treated tumor cells in a CD4+ T cell–dependent manner, suggesting that it may contribute to IL-24 induction in macrophages." (PMID 39782693, 2025). "TLR-4 engagement is crucial for activating innate immunity and enhancing the adaptive immune response, indicating that our vaccine constructs have the potential to trigger a comprehensive anti-tumor response." (PMID 40599850, 2025). "In inflammatory contexts, local B1R and TLR4 expression supports the hypothesis that DBK enhances drug bioavailability to the tumor mass." (PMID 40284027, 2025). "Furthermore, in an LLC cell model, IL‐10 enhanced tumor cell resistance to apoptosis and activated the TLR4/IL‐10 cascade reaction, thus promoting tumor cell EMT." (PMID 39927632, 2025). "To assess the PCa tumour microenvironment for impaired immunity, we also performed a pilot RNA-expression analysis for PCa-associated immunological factors (IL1β, IL10, IL18, TNF-α, TLR4, GATA3, CD68)." (PMID 40430084, 2025). "Moreover, Wang Ruonan’s team designed a DC-targeting nanoregulator (DNR) that reprograms dendritic cells in tumor-draining lymph nodes (TDLNs) by synergistically activating TLR4 (via mannan) and TLR7/8 (via an IMDQ prodrug) signaling pathways." (PMID 41488647, 2025). "TLR4 expression is cell type and stage-specific and can be affected by the different tumorigenic and metastasis processes, immune capacities of cancer cells, and particularly differences in the immune cells infiltrating the tumor." (PMID 40809181, 2025). "Preclinical evidence demonstrates that Moringa oleifera modulates important signaling pathways, including YAP/TAZ, Wnt/β-catenin, Nrf2-Keap1 and TLR4/NF-κB, which play divergent roles depending on the tumor cellular context, microenvironment, and cancer-related immune-metabolic axis." (PMID 41516140, 2025).
tumor (continued). "Calreticulin, ATP, and HMGB1 bind to CD91, P2RX7, and TLR4, respectively, facilitating dendritic cell (DC) recruitment into the tumor bed (by ATP), the phagocytosis of tumor antigens by DCs (enhanced by CRT), and an optimal antigen presentation to T cells (stimulated by calreticulin and HMGB1)." (PMID 40313247, 2025). "However, the ligand that initiates TLR4 signaling in tumor cells in particular has been a subject of intense debate." (PMID 40124677, 2025). "HMGB1, released by dying tumor cells, may be recognized by DCs in a Toll-like receptor 4 (TLR4)- and myeloid differentiation primary response gene 88 (MyD88)-dependent manner, leading to a potent immune response." (PMID 39857785, 2025). "Furthermore, USP11 deficiency suppressed tumor spheroid formation in response to EGF, HKLM (a TLR2 agonist), and LPS (a TLR4 agonist), whereas USP11 overexpression amplified these effects." (PMID 41419456, 2025). "The results in in-vivo models confirmed the hypothesis that YGS might inhibit tumor immune escape by sensitizing CRC stem cells via the NF-κB pathway through targeting TLR4, and YGS could inhibit the EMT process of CRC at the tissue level." (PMID 40247422, 2025). "We also tested TLR4, and it was slightly increased in tumor spheres compared to adherent cells." (PMID 40647457, 2025). "Research on an H22 HCC mouse model highlighted the robust anti-tumor potential of salvianolic acid B. The findings revealed that salvianolic acid B not only curbed tumor growth but also mitigated inflammation-related immune activity by regulating the TLR4/MyD88/NF-κB pathway." (PMID 39972480, 2025). "F. nucleatum has been reported to impair immune surveillance and weaken anti-tumor immune responses by reducing T cell infiltration and activating pro-inflammatory pathways such as TLR4 signaling, thereby promoting tumor growth, immune evasion, and metastasis in colorectal cancer." (PMID 40136500, 2025). "HMGB1 promotes tumor invasion and metastasis via activation of TLR4 and RAGE signaling pathways." (PMID 41354099, 2025). "Furthermore, deregulated TLR4 signaling in tumor cells can lead to an inflammatory response, which potentiates tumor cells’ resistance towards cell death, proliferation, invasion, and metastasis." (PMID 41383620, 2025). "The TLR4/Myd88/NF-κB axis promotes the development of tumours." (PMID 39735680, 2025). "However, the incorporation of TLR domains has shown variable results depending on tumor type, with TLR4 constructs responding more slowly in solid tumors, despite achieving remission in preclinical models." (PMID 39941106, 2025). "In addition, activation of TLR4 upregulates the expression of programmed death ligand 1 (PD-L1), which in turn inhibits the anti-tumor activity of T cells and promotes immune escape." (PMID 40166469, 2025). "TLR4 influences tumor growth through its effects on cancer metabolism and the immune response." (PMID 40656954, 2025). "While lipid-based nanoparticles have been primarily utilized to prevent mRNA degradation and improve delivery to antigen-presenting cells, some have also been shown to activate TLR4 signaling and thereby increase anti-tumor vaccine efficacy in murine tumor models." (PMID 41012179, 2025). "Therefore, TLR4 inhibitors can influence immune responses and tumor invasion, offering significant research potential for targeted therapy in OS." (PMID 41296391, 2025). "Because of this characteristic, saponins are frequently found in liposomes, nanoparticles, and other forms of nanoparticles for use in tumor immunotherapy, complementing Toll-like receptor 4 (TLR4) agonists and boosting helper cell and cytotoxic T cell responses." (PMID 41451199, 2025). "Mechanistically, perivascular Tenascin C produced by tumor cells activates TLR4-dependent perivascular macrophages within pre-metastatic niches, resulting in upregulated expression of NO and TNF to induce endothelial cells-mediated production of niche components." (PMID 41417432, 2025).
tumor (continued). "TLR4 can have opposing effects, however, depending on the context and may confer a survival advantage for the tumor cells." (PMID 40592236, 2025). "Moreover, an inverse correlation was observed between TLR4 expression in deep tumor invasion front and PD‐L1 average expression, as well as with PD‐L1 in the superficial tumor front (r = −0.348, p = 0.014 and r = −0.269, p = 0.049, respectively)." (PMID 40762187, 2025). "The activation of TLR2/TLR4 by HSPs causes the activation of HSF1 signaling followed by NF-kB signaling in DCs, resulting in the release of cytokines (IL-1, IL-6, and TNF) and the release of tumor antigens, which can be processed by APCs." (PMID 41375025, 2025). "Studies have shown that Fusobacterium nucleatum can induce neutrophil extracellular traps (NETs) formation via the TLR4-ROS and NOD1/2 signaling pathways in neutrophils, accelerate tumor growth, and promote tumor metastasis, manifested as EMT-associated cell migration." (PMID 41019090, 2025). "Master regulator of tumor suppression, controls immune response, regulates TLR4." (PMID 41409896, 2025). "Therefore, the TLR4 expression level in tumor tissues and NSCLC cell lines was measured by western blotting." (PMID 40817754, 2025). "In our study, high TLR4 expression was significantly associated with increased M2 macrophage infiltration (Rho = 0.74, p < 0.001), suggesting that TLR4 may enhance tumour immune evasion by promoting M2 macrophage infiltration." (PMID 40696496, 2025). "Furthermore, a Western blot assay was used to analyze tumor samples, which showed elevated levels of TLR4 and p-p65 in the 216911KO tumors, indicating the activation of the TLR4/NFκB/NLRP3 signaling pathway." (PMID 39824843, 2025). "These could include therapies targeting obstruction-related pathways, such as hypoxia (e.g., HIF inhibitors) or bacterial-driven inflammation (e.g., TLR4 antagonists), to resensitize the tumor microenvironment." (PMID 41301691, 2025). "Activation of NLRP3, TLR3 and TLR4 may lead to chronic inflammation, which contributed to immune evasion and tumor progression." (PMID 40535567, 2025). "Interestingly, the same large amount of HMGB1 was released in dead cells after treatment with doxorubicin, which mediated the survival of chemoresistant tumor cells through TLR4/RAGE-sCLU." (PMID 40969278, 2025). "Deletion of TLR4 protected TLR4–/– mice from tumor progression." (PMID 40585846, 2025). "By combining TAK242 with radiation, we aimed to explore whether targeting TLR4 can improve radiosensitivity, reduce tumor growth, and counteract the mechanisms of radioresistance." (PMID 41332426, 2025). "Fibroblasts also interact with TLR-4 in the tumor microenvironment." (PMID 40404908, 2025). "Notably, in the tumor microenvironment, tumor-derived stimuli such as granulocyte G-CSF, IL-8, and tumor exosomes trigger ROS-dependent suicidal NETosis via the TLR4 signaling pathway." (PMID 40528159, 2025). "Furthermore, TLR4 on DCs presents tumor antigens from dying cancers to activate cytotoxic T cells for fighting cancer." (PMID 38903515, 2024). "Moreover, it reversed the BC inhibitory effects of PUM2 OE and was accompanied by decreased expression of SASH1, a protein with tumor suppressor activity in TNBC involved in the toll-like receptor 4 (TLR4) signaling pathway." (PMID 38339387, 2024). "Proinflammatory chemokines and immunosuppressive cytokines are produced irregularly and uninhibitedly by TLR-4 during tumor progression; this suggests that finding TLR-4 antagonists could be a great way to treat cancer." (PMID 39770406, 2024). "A rescue experiment showed that TLR4 overexpression could counteract the tumor-inhibitory roles of miR-5195-3p in CRC cell behaviors by enhancing TLR4/MyD88 signaling." (PMID 39390599, 2024). "The expression of TLR4 protein was also more in BC tumor than that in paracancerous tissue." (PMID 38833016, 2024).